CMKLR2 (chemerin chemokine-like receptor 2)
Description:
Receptor for chemoattractant adipokine chemerin/RARRES2 suggesting a role for this receptor in the regulation of inflammation and energy homesotasis. Signals mainly via beta-arrestin pathway. Binding of RARRES2 activates weakly G proteins, calcium mobilization and MAPK1/MAPK3 (ERK1/2) phosphorylation too. Also acts as a receptor for TAFA1, mediates its effects on neuronal stem-cell proliferation and differentiation via the activation of ROCK/ERK and ROCK/STAT3 signaling pathway (By similarity). (Microbial infection) Coreceptor for HIV-1.
Synonyms: GPR1
Tractability: Small molecule: a structure with a bound ligand is known; it belongs to a druggable protein family. Antibody: UniProt places it where antibodies can reach, with high confidence; its Gene Ontology location is reachable by antibodies, with high confidence; UniProt predicts a signal peptide or a membrane-spanning region; the Human Protein Atlas places it where antibodies can reach.
Target class: Family A G protein-coupled receptor; Membrane receptor
Gene: Protein-coding gene on chromosome 2 (206,175,316 to 206,218,047, reverse strand). Ensembl gene ENSG00000183671.
Subcellular location: Cell membrane
Subcellular location (Human Protein Atlas): Plasma membrane; Nucleoplasm; Vesicles
Gene Ontology:
Molecular function: adipokinetic hormone binding; adipokinetic hormone receptor activity; protein binding; G protein-coupled receptor activity; neuropeptide binding
Biological process: G protein-coupled receptor signaling pathway; glucose homeostasis; neuropeptide signaling pathway; regulation of inflammatory response; signal transduction
Cellular component: G protein-coupled receptor complex; plasma membrane; neuron projection; membrane
Genetic constraint (gnomAD): Loss-of-function variants: 17 observed, 24.14 expected, observed/expected ratio (o/e) 0.7, 90% interval 0.48 to 1.06. The upper end of that interval is the gene's LOEUF score, 1.06, which puts it in group 4 of 6, group 1 being the genes least tolerant of losing a copy. Missense variants: 389 observed, 423.97 expected, observed/expected ratio (o/e) 0.92, 90% interval 0.84 to 1. Synonymous variants: 152 observed, 162.8 expected, observed/expected ratio (o/e) 0.93, 90% interval 0.82 to 1.07.
Homologues: Orthologues: chimpanzee CMKLR2 (99% identical), macaque CMKLR2 (98% identical), dog CMKLR2 (90% identical), rabbit CMKLR2 (89% identical), pig CMKLR2 (87% identical), mouse Cmklr2 (80% identical), rat Cmklr2 (79% identical), tropical clawed frog cmklr2 (52% identical), zebrafish cmklr2 (37% identical), Caenorhabditis elegans trhr-1 (21% identical), Drosophila melanogaster Rh7 (20% identical). Paralogues in human: SSTR4 (28% identical), PTGDR2 (28% identical), OPRK1 (27% identical), OPRL1 (27% identical), SSTR5 (27% identical), OPRD1 (27% identical), OPRM1 (26% identical), SSTR2 (25% identical), NPBWR2 (24% identical), SSTR3 (24% identical), NPBWR1 (23% identical), SSTR1 (23% identical), and 5 more.
Diseases named in the same sentence as CMKLR2 in open-access papers:
CMKLR2 is named in the same sentence as 39 diseases in open-access papers, as found by Europe PMC text mining. Sharing a sentence is not in itself a finding about the gene and the disease. The quoted sentences say what the papers report.
tumor (17 papers, 2016 to 2025). "In accord with these findings the levels of chemerin receptor 23 (ChemR23, also called CMKLR2) were augmented in tumor challenged mice that were treated with Poly(I:C)." (PMID 27198666, 2016).
inflammation (1 paper, 2024). Aberrant reaction of the microcirculation characterized by movement of fluid and leukocytes from the blood into extravascular tissues. "Thus, if CMKLR2 exerts the opposite effect on O3‐induced lung injury and lung inflammation than that which occurs when CMKLR1 is absent, no net effect on any indice would manifest in CMKLR1‐deficient mice." (PMID 38631890, 2024).
CMKLR2 also shares sentences with these, for which no sentence is quoted: ovarian carcinoma (34 papers); cancer (10); Obesity (9); Glucose intolerance (6); gastric cancer (5); breast carcinoma (4); infection (4); essential hypertension (3); inflammatory bowel disease (2); neuroblastoma (2); Alzheimer disease (1); cardiomyopathy (1); cardiovascular diseases (1); coronary artery disease (1); cutaneous squamous cell carcinoma (1); depression (1); diabetes (1); gastric adenocarcinoma (1); gastric tumors (1); gestational diabetes mellitus (1); glioblastoma (1); head and neck squamous cell carcinoma (1); hyperandrogenism (1); Hypertension (1); idiopathic pulmonary fibrosis (1); Infertility (1); metabolic disease (1); neurodegenerative disease (1); neuroendocrine colon tumor (1); non-small cell lung carcinoma (1).
A further 7 diseases each share a sentence with CMKLR2 in 1 paper.